SQSTM1 (sequestosome 1)
Diseases named in the same sentence as SQSTM1 in open-access papers (continued):
Sharing a sentence is not in itself a finding about the gene and the disease.
atrial fibrillation (1 paper, 2018). A disorder characterized by an electrocardiographic finding of a supraventricular arrhythmia characterized by the replacement of consistent P waves by rapid oscillations or fibrillatory waves that vary in size, shape and timing and are accompanied by an irregular ventricular response. "The myopathic respiratory insufficiency and atrial fibrillation (although the latter finding could an incidental finding) in family 2’s proband emphasize the need to investigate respiratory and cardiac function in future cases of SQSTM1/TIA1 myopathy." (PMID 29599744, 2018).
bacterial sepsis (1 paper, 2023). "Patients with bacterial sepsis show increased levels of SQSTM1 and INSR mRNA in peripheral blood mononuclear cells, along with elevated serum SQSTM1 concentrations." (PMID 38020710, 2023).
benign ovarian tumor (1 paper, 2021). "Meanwhile, IHC scores of SHH and SQSTM1 were higher in borderline ovarian tumors and even higher than those in benign ovarian tumors." (PMID 34076346, 2021).
bone osteosarcoma (1 paper, 2018). A usually aggressive malignant bone-forming mesenchymal neoplasm arising from the bone. "We thus evaluated the levels of lipidated LC3B and SQSTM1 in human bone osteosarcoma epithelial U2OS cells treated with equimolar doses of N1-methyspermidine and spermidine." (PMID 29590104, 2018).
Buruli ulcer (1 paper, 2022). "Increased SQSTM1 staining could be seen in Buruli ulcer patient skin biopsy samples, reinforcing genetic data that suggests autophagy is relevant to disease pathology." (PMID 34424124, 2022).
CADASIL (1 paper, 2022). "Patients with CADASIL were found to have SQSTM1 gene mutations, with the damaged NOTCH3 and p62 genes encoding key proteins in the autophagic lysosomal pathway." (PMID 36139821, 2022).
cataract (1 paper, 2023). Partial or complete opacity of the crystalline lens of one or both eyes that decreases visual acuity and eventually results in blindness. "In this model, cataracts are associated with the accumulation of SQSTM1-positive aggregates due to insufficient autophagy and increased αB-crystallin aggregation." (PMID 37034386, 2023). "Mice deficient in Fyco1 exhibit normal lens organelle degradation, but develop age-associated cataracts with the accumulation of SQSTM1, insoluble crystallin, and some organelles in differentiating lens fiber cells around the OFZ." (PMID 37034386, 2023). "Next, lens-specific Atg5-deficient mice show accumulation of autophagic substrates such as polyubiquitinated proteins and SQSTM1 and eventually develop ageassociated cataracts with increased levels of oxidized proteins and insoluble crystallins." (PMID 37034386, 2023).
childhood asthma (1 paper, 2025). "SQSTM1, HSPA5, and A2M which directly interact with RETN could serve as the potential therapeutic targets in childhood asthma." (PMID 41550933, 2025). "The resistin protein-protein interaction network analysis further suggests that SQSTM1, HSPA5 and A2M might serve as the potential therapeutic targets in childhood asthma." (PMID 41550933, 2025).
chondrosarcoma (1 paper, 2024). A malignant cartilaginous matrix-producing mesenchymal neoplasm arising from the bone and soft tissue. "Moreover, osteoblastic osteosarcoma exhibited a higher expression of SQSTM1 compared to chondrosarcoma." (PMID 39015499, 2024).
chordoma (1 paper, 2021). Chordomas are rare malignant tumors arising from embryonic remnants of the notochord in axial skeleton. "All chordomas strongly and diffusely expressed cytoplasmic p62 (sequestosome 1, SQSTM1/p62), whereas 16 (26.2%) tumors also showed nuclear p62 expression." (PMID 33946484, 2021).
chronic obstructive pulmonary disease (1 paper, 2019). A chronic and progressive lung disorder characterized by the loss of elasticity of the bronchial tree and the air sacs, destruction of the air sacs wall, thickening of the bronchial wall, and mucous accumulation in the bronchial tree. "For example, patients with chronic obstructive pulmonary disease (COPD) with increased levels of Il-6, Il-8, TNF-α demonstrated decreased levels of SQSTM1/p62 in PBMCs." (PMID 30633777, 2019).
clear cell renal cell carcinoma (1 paper, 2023). "SQSTM1 protein is an oncogene that its overexpression in clear cell renal cell carcinoma increases resistance to redox stress, and its reduction has the opposite effect and reduces tumor formation." (PMID 38224029, 2023).
co-infection (1 paper, 2016). "Similar to the protein levels, SQSTM1 showed an increased gene expression upon co-infection, but in contrary to the protein levels gene expression analysis revealed that SQSTM1 was unaffected or even increased with Torin1 treatment." (PMID 27302320, 2016).
Crohn disease (1 paper, 2021). A gastrointestinal disorder characterized by chronic inflammation involving all layers of the intestinal wall, noncaseating granulomas affecting the intestinal wall and regional lymph nodes, and transmural fibrosis. "Our results indicate that the ATG16L1 T300A Crohn's disease-associated SNP causes a decrease in migration capacity in epithelial cells, mediated by an increase in SQSTM1 and ARHGAP18 protein and subsequent reduced RhoA activation." (PMID 33973626, 2021).
cyst (1 paper, 2025). A sac-like closed membranous structure that may be empty or contain fluid or amorphous material. "In addition, the autophagy gene Sequestosome-1/p62 (SQSTM) was upregulated in the diapause cyst of Acartia tonsa, which is a gene that functions in the stress response." (PMID 40004504, 2025).
cystic fibrosis (1 paper, 2025). Autosomal recessive disorder caused by pathogenic variants in the CFTR gene (cystic fibrosis transmembrane conductance regulator), which encodes a chloride and bicarbonate channel expressed in epithelial cells, and follow the diagnosis criteria. "Consequently, the autophagy substrate SQSTM1/p62 accumulates, trapping misfolded F508del-CFTR and key anti-inflammatory proteins such as PPARγ and IκBα in intracellular aggresomes, perpetuating a pro-inflammatory environment in cystic fibrosis airways." (PMID 40430792, 2025).
depression (1 paper, 2018). "Furthermore, the chronic absence of SQSTM1/p62 promotes neurodegeneration with neurofibrillary tangles in hippocampal and cortical neurons manifesting with depression and short-term memory decline, which is similar to the clinical presentations of the present patient." (PMID 29467647, 2018).
Diplopia (1 paper, 2025). Diplopia is a condition in which a single object is perceived as two images, it is also known as double vision. "We report the case of a patient presenting with diplopia, ptosis, and blurred vision who was found to have a heterozygous SQSTM1 gene variant (c.1175C>T) following electrophysiological evidence of a postsynaptic neuromuscular junction disorder." (PMID 40772172, 2025).
disc degeneration (1 paper, 2025). "Persistent NF-κB activation driven by abnormal SQSTM1 accumulation can sustain inflammation, contributing to disc degeneration." (PMID 40933658, 2025). "Recent studies have highlighted the significant role of SQSTM1 in autophagy, inflammation, and cell death, making it a promising candidate for clinical applications in intervertebral disc degeneration (IDD)." (PMID 40933658, 2025). "Given its dynamic expression during disc degeneration, SQSTM1 holds promise as both a biomarker for IDD progression and a therapeutic target." (PMID 40933658, 2025).
dysferlinopathy (1 paper, 2021). "Muscles from dysferlinopathy patients show elevated MuRF-1, LC3-II, p62/SQSTM1 and Bnip3 levels, and fiber atrophy phenotypically." (PMID 33841177, 2021).
Dysmetria (1 paper, 2020). A type of ataxia characterized by the inability to carry out movements with the correct range and motion across the plane of more than one joint related to incorrect estimation of the distances required for targeted movements.
encephalitis (1 paper, 2023). An acute inflammatory process affecting the brain parenchyma. "During Sindbis virus (SINV) infection, autophagy protein Beclin 1 protects against SINV-mediated encephalitis, and p62 (also called sequestosome 1 (SQSTM1)) binds to a SINV capsid protein targeting it to the autophagosome." (PMID 37277829, 2023).
endometriosis (1 paper, 2022). The growth of functional endometrial tissue in anatomic sites outside the uterine body. "The expression of Beclin1 was significantly increased, the ratio of LC3II/I was increased, and the expression of SQSTM1/p62 was decreased, which indicated that autophagy was activated and its level was anormal in the ectopic lesions of patients with endometriosis." (PMID 36263059, 2022).
experimental autoimmune encephalomyelitis (1 paper, 2020). An autoimmune demyelinating disease of the central nervous system that is produced experimentally in animals by the injection of homogenized brain or spinal cord in Freund's adjuvant. "In addition, in experimental autoimmune encephalomyelitis (EAE), an MS mouse model, LC3 and BECLIN1 protein levels were reduced while those of p62/SQSTM1 were increased in the spinal cords of these animals." (PMID 33328897, 2020).
focal cortical dysplasia type 2B (1 paper, 2021). "Several studies have shown increased levels of SQSTM1 within TSC tubers and focal cortical dysplasia type 2B." (PMID 34287356, 2021).
gastric adenocarcinoma (1 paper, 2017). "We demonstrate that gastrin increases the expression of the autophagy markers MAP1LC3B-II and SQSTM1 in gastric adenocarcinoma cells." (PMID 28109268, 2017).
Gaucher disease (1 paper, 2023). Gaucher disease (GD) is a lysosomal storage disorder encompassing three main forms (types 1, 2 and 3), a fetal form and a variant with cardiac involvement (Gaucher disease - ophthalmoplegia - cardiovascular calcification or Gaucher-like disease). "Accumulation of p62/SQSTM1 has been reported in the endosomal/lysosomal fraction of npc1-/- mouse brain lysates, cultured fibroblasts of Fabry patients, mucolipidosis type II, III and type IV (MLIV) fibroblasts, muscle fibers of Pompe disease, and brain of Gaucher disease mice model." (PMID 36928510, 2023).
goiter (1 paper, 2024). Enlargement of the thyroid gland usually caused by lack of iodine in the diet, hyperthyroidism, or thyroid nodules. "NCOA4 fusion was associated with patients’ sex, multifocality, microcarcinoma character, medical history of goiter, and obstructive pulmonary disease, while SQSTM1 fusion was linked with multifocality and medical history of thyroid/parathyroid adenoma." (PMID 39409115, 2024).
hereditary cardiomyopathies (1 paper, 2024). "In hereditary cardiomyopathies causing arrhythmias, autophagy markers like LC3 and SQSTM1/p62 and autophagic vacuoles are detected in arrhythmogenic cardiomyopathy and LAMP2 cardiomyopathy." (PMID 39010053, 2024).
Hypercholesterolemia (1 paper, 2018). An increased concentration of cholesterol in the blood. "Ezetimibe, a drug approved by the Food and Drug Administration (FDA) for the treatment of hypercholesterolemia, improves NAFLD and alleviates oxidative stress by the activation of AMPK, which in turn phosphorylates p62/SQSTM1." (PMID 30249977, 2018).
Hypoglycemia (1 paper, 2020). A decreased concentration of glucose in the blood. "Similar to the parietal cortex in the hippocampus LC3-II significantly increased 2 h after hypoglycemia, while no significant change in SQSTM1/p62 was found." (PMID 33173467, 2020).
hypopharyngeal carcinoma (1 paper, 2023). Carcinoma, predominantly squamous cell, arising from the epithelial cells of the hypopharynx. "Based on the important biological function of SQSTM1, we first explored the expression of SQSTM1 in hypopharyngeal carcinoma tissues through immunohistochemical (IHC) analysis." (PMID 37944249, 2023). "In conclusion, HOXC-AS can exert its biological effect and regulate the progression of hypopharyngeal cancer by binding to SQSTM1 to regulate NF-KB expression." (PMID 37944249, 2023). "SQSTM1 was highly expressed in hypopharyngeal carcinoma tissues compared with normal tissues." (PMID 37944249, 2023).
ileitis (1 paper, 2025). "Loss of the autophagy-related gene Atg16l1 inhibited the degradation of TRIF mediated by autophagy receptors SQSTM1 and Tax1BP1, thus driving TRIF-dependent inflammatory signaling in S. Typhimurium-induced ileitis." (PMID 39809743, 2025).
infarction (1 paper, 2018). A localised pathological necrosis of tissue resulting from obstruction of the blood supply usually by a thrombus, an embolus, or vascular torsion. "Furthermore, LC3-II to LC3-I ratio was increased but the SQSTM1/p62 expression was decreased in the TGC-treated MI hearts, suggesting that TGC causes enhanced autophagy in cardiomyocytes in response to myocardial ischemia and infarction." (PMID 29872406, 2018).
injury (1 paper, 2017). Damage inflicted on the body as the direct or indirect result of an external force, with or without disruption of structural continuity. "Decreased Sqstm1 mRNA expression levels following insult have also been shown for other brain pathologies like hypoxic-ischemic brain injury." (PMID 29311767, 2017).
invasive ductal carcinoma (1 paper, 2021). "Using a tissue microarray from 274 breast invasive ductal carcinoma (IDC) patients, we found that tumor tissues showed higher protein levels of MAP1LC3B and cytoplasmic SQSTM1 in comparison to those in adjacent normal tissues." (PMID 34829743, 2021).
knee osteoarthritis (1 paper, 2021). "In vivo, sustained static compression-induced decreases in rat disc LC3-II and p62/SQSTM1 are compatible with a prior mouse knee osteoarthritis study, showing progressive decreases in Atg protein expression after transection of the medial meniscotibial and collateral ligaments." (PMID 34073333, 2021).
leprosy (1 paper, 2017). Leprosy is a chronic infectious disease affecting primarily the skin and peripheral nervous system. "Dialyzed proteins from leprosy skin biopsies were evaluated by commercial ELISA assays for SQSTM1/p62 and NBR1." (PMID 28056107, 2017).
liver failure (1 paper, 2015). A liver disease characterized by the liver losing or has lost all of its function. "Persistent activation of Nrf2 due to sequestration of Keap1 into Sqstm1-positive structure causes hepatomegaly and liver failure in Atg7f/f;Albumin-Cre and Atg5f/f;Albumin-Cre mice." (PMID 26483381, 2015).
lung squamous cell carcinoma (1 paper, 2025). "By including the increase in expression of the SQSTM1 gene in the analysis of five genes, lung squamous cell carcinoma (LUSC; HR = 1.3, p = 0.042) and liver hepatocellular carcinoma (LIHC; HR = 1.4, p = 0.042)." (PMID 41472277, 2025).
male infertility (1 paper, 2025). The inability of the male to effect fertilization of an ovum after a specified period of unprotected intercourse. "Similarly, in male mice, deltamethrin administration caused testicular damage, accompanied by a decrease in p62/SQSTM1 protein levels, enhancing autophagy flux and contributing to male infertility." (PMID 41465325, 2025).
malignant glioma (1 paper, 2016). A grade III or grade IV glioma arising from the central nervous system. "SQSTM1 has been identified as a component of inclusion bodies found in various human diseases including HCC and malignant glioma." (PMID 27145374, 2016).
malignant mesothelioma (1 paper, 2017). A malignant neoplasm of the pleura or peritoneum, arising from mesothelial cells. "Overall, these findings demonstrate that Tan I exerts antitumor activity through a compromise between apoptosis and p62/SQSTM1-dependent autophagy via activation of JNK and IRE 1 in malignant mesothelioma cells." (PMID 28212571, 2017). "Thus, in the current study, an autophagic molecular mechanism of Tan I was elucidated by assessing the essential effect of p62ΔUBA domain andprotein- protein interactions between p62/SQSTM1 and JNK or IRE1 in H28 and H2452 malignant mesothelioma cells." (PMID 28212571, 2017).
medulloblastoma (1 paper, 2019). A malignant, invasive embryonal neoplasm arising from the cerebellum. "Expression levels of p62/SQSTM1 increased upon miR-204 expression in the three medulloblastoma cell lines further confirming autophagy inhibition." (PMID 30944042, 2019). "In the present study as well, miR-204 expression in medulloblastoma cells resulted in reduction in the LC3B flux and increase in the levels of p62/SQSTM1 indicating autophagy inhibition." (PMID 30944042, 2019).
MELAS (1 paper, 2024). "In contrast, there were no significant changes in LAMP1, SQSTM1 and LC3B-II protein levels in skin fibroblasts from m.3243 A > G MELAS patients." (PMID 38741129, 2024).
metastatic melanoma (1 paper, 2019). A melanoma that has spread from its primary site to another anatomic site. "In metastatic melanomas, expression of sequestosome 1/SQSTM1/p62 (p62) is higher, associated with poor patient prognosis." (PMID 31801551, 2019).
mucoepidermoid carcinoma (1 paper, 2019). A carcinoma morphologically characterized the presence of cuboidal mucous cells, goblet-like mucous cells, squamoid cells, cystic changes, and a fibrotic stromal formation. "Although little is known concerning the role of HDAC7 on autophagy, its inhibition in mucoepidermoid carcinoma cells, using siRNA also blocks cell proliferation and promotes autophagy (accumulation of LC3B-II and acidic vesicles and decrease of SQSTM1/P62 content)." (PMID 31861179, 2019).
multiple system atrophy (1 paper, 2021). Multiple system atrophy (MSA) is a neurodegenerative disorder characterized by autonomic failure (cardiovascular and/or urinary), parkinsonism, cerebellar impairment and corticospinal signs with a median survival of 6-9 years. "SQSTM1 (p62), a cargo protein which binds to autophagy substrates and is degraded with them colocalizes with tau and α-synuclein aggregates in the brain of patients with various neurodegenerative diseases including AD, PSP, Lewy body disease and multiple system atrophy." (PMID 34727983, 2021).
muscular atrophy (1 paper, 2017). The loss of muscle tissue due to inactivity or disease. "Rapid upregulation after denervation of several E3 ligases and autophagy-related proteins, including NBR1 and sequestosome-1, indicates that M-band proteins are most likely to be the first proteins targeted for breakdown during muscular atrophy." (PMID 28546288, 2017).
Myocardial fibrosis (1 paper, 2018). "The number of p62/SQSTM1-positive BD-inclusions/mm2 in the left ventricle was associated with the degree of myocardial fibrosis (Linear regression analysis – myocardial fibrosis: R2 = 0.073, β = 0.270, p = 0.033)." (PMID 30413735, 2018). "p62/SQSTM1-positive sAPPδ/η aggregates in cardiomyocytes representing BD are associated with age confirming previous studies on BD3,5–7 and with myocardial fibrosis in the left ventricle of hypertensive individuals." (PMID 30413735, 2018).
myocardial infarction (1 paper, 2021). Gross necrosis of the myocardium, as a result of interruption of the blood supply to the area, as in coronary thrombosis. "Simvastatin promotes the translocation of Parkin and p62/SQSTM1 and activates mitophagy, thus inhibiting the infarct size in cellular and mouse myocardial infarction models." (PMID 34603595, 2021).
myocarditis (1 paper, 2023). Myocarditis is a condition that is characterized by inflammation of the heart muscle (myocardium). "The collection of evidence demonstrates that CVB3-induced myocarditis can impair cardiac function by cleaving host proteins involved in the immune response, including MAVs, TRIF, NFAT5, SQSTM1, and CARD8, to impair host defense mechanisms and promote pyroptosis and apoptosis." (PMID 37175422, 2023).